LZTR1 (leucine zipper like post translational regulator 1)
Diseases named in the same sentence as LZTR1 in open-access papers (continued):
Sharing a sentence is not in itself a finding about the gene and the disease.
leukemia (2 papers, 2023 to 2024). A malignant (clonal) hematologic disorder, involving hematopoietic stem cells and characterized by the presence of primitive or atypical myeloid or lymphoid cells in the bone marrow and the blood. "A minor intron retention of LZTR1 is associated with tumorigenesis in leukemias." (PMID 38067392, 2023). "Similarly, ZRSR2 loss increased retention of a minor intron of LZTR1, which resulted in enhanced RAS signaling, potentially driving leukemia." (PMID 38067392, 2023).
Li-Fraumeni syndrome (2 papers, 2021 to 2022).
lung adenocarcinoma (2 papers, 2023 to 2024). A carcinoma that arises from the lung and is characterized by the presence of malignant glandular epithelial cells. "In lung adenocarcinoma cells, LZTR1 deficiency induced the accumulation of the RAS subfamily and enhanced cell proliferation, invasion, and xenograft tumor growth." (PMID 37626065, 2023). "LZTR1 encodes a protein that regulates polyubiquitination and degradation of RAS proteins and has been suggested to regulate the growth and invasion of lung adenocarcinoma cells through RAS/MAPK signaling." (PMID 38975340, 2024). "To investigate the role of LZTR1 in cancer, we generated an LZTR1 knockout A549 cell line, a human lung adenocarcinoma cell line (A549-KO)." (PMID 37626065, 2023). "Here, we demonstrated that the loss of LZTR1 could induce the accumulation of RIT1 and KRAS in lung adenocarcinoma cells and promote tumor growth and metastasis." (PMID 37626065, 2023). "LZTR1 deficiency increased RIT1 and KRAS expression in lung adenocarcinoma cells." (PMID 37626065, 2023).
lung carcinoma (2 papers, 2023 to 2025). "Next, we investigated the effect of LZTR1 deficiency on EMT induction in lung cancer cells." (PMID 37626065, 2023). "From a therapeutic perspective, the reduction of RIT1 may provide benefits in lung cancer therapy with or without LZTR1 mutations." (PMID 37626065, 2023).
metastatic tumors (2 papers, 2020 to 2023). "Further, we found that LZTR1 deficiency significantly increases lung metastasis and promotes ECM deposition around metastatic tumors." (PMID 37626065, 2023). "Other genes, such as BCORL1 (OVA_003), CASP3 (OVA_047), CHD2 (OVA_013), FAT3 (OVA_365) and LZTR1 (OVA_378), were heterogeneous, having differing clonality in the primary versus the metastatic tumours." (PMID 32099096, 2020).
myelodysplastic syndrome (2 papers, 2024). A clonal hematopoietic disorder characterized by dysplasia and ineffective hematopoiesis in one or more of the hematopoietic cell lines. "One of these patients, determined with LZTR1 variant rs869320686 p.(Gly248Arg), developed a myelodysplastic syndrome (MDS) 2.1 years after undergoing hyperdiploid pre B-cell ALL." (PMID 38413718, 2024). "Due to the aberrant splicing of LZTR1 (leucine zipper-like transcriptional regulator 1), mutations in the splicing factor ZRSR2 have been associated with a number of illnesses, including myelodysplastic syndromes (MDS) and predispositions to cancer." (PMID 39584923, 2024).
ptosis (2 papers, 2019 to 2025). The drooping of the upper eyelid. "In one patient, a girl with pulmonary valve stenosis, short stature, recurrent chylothorax, ptosis, and typical facial dysmorphism, two novel compound heterozygous variants in LZTR1 (p.Asp668Gly; p.Gln762_Glu765del) were identified." (PMID 40332000, 2025).
acute monocytic leukemia (1 paper, 2023). Acute monoblastic leukemia (AML-M5), is one of the most common subtypes of acute myeloid leukemia (AML) that is either comprised of more than 80% of monoblasts (AML-M5a) or 30-80% monoblasts with (pro)monocytic differentiation (AML-M5b). "In contrast, LZTR1 deficiency increased RIT1, KRAS, MRAS, and NRAS expression in fetal liver and acute monocytic leukemia cells." (PMID 37626065, 2023).
autoimmune disease (1 paper, 2025). A disorder resulting from loss of function or tissue destruction of an organ or multiple organs, arising from humoral or cellular immune responses of the individual to their own tissue constituents. "Furthermore, our data highlight MHC-I and LZTR1 as novel therapeutic targets in autoimmune diseases, especially for patients prone to recurrent episodes." (PMID 41162356, 2025). "In summary, these data identify LZTR1 as a novel regulator of CD8+ TRM function and provide insights into the mechanisms that drive and maintain CD8+ T-cell responses in epithelial-associated autoimmune diseases." (PMID 41162356, 2025).
Autoimmunity (1 paper, 2025). The occurrence of an immune reaction against the organism's own cells or tissues. "Here, we identify a novel mechanism in autoimmunity and activation of CD8+ T cells, particularly CD8+ TRM cells, through modulation of MHC-I expression by LZTR1 in an NF-κB1-dependent manner." (PMID 41162356, 2025).
B-cell neoplasm (1 paper, 2021). A group of heterogeneous lymphoid tumors generally expressing one or more B-cell antigens or representing malignant transformations of B-lymphocytes. "Out of 15 patients, 4 (26.6%) with subsequent mature B-cell neoplasms had germline pathogenic mutations in cancer susceptibility genes; MUTYH and WRN in 2 subsequent DLBCL patients and RAD50 and LZTR1 in 2 subsequent PCM patients." (PMID 34093829, 2021).
colorectal cancer (1 paper, 2025). A primary or metastatic malignant neoplasm that affects the colon or rectum. "Clinically, LZTR1 expression is frequently downregulated in KRAS-driven malignancies such as pancreatic and colorectal cancers, correlating with elevated KRAS stability and MAPK hyperactivation." (PMID 40427667, 2025).
Costello syndrome (1 paper, 2019). Costello syndrome (CS) is a rare multisystemic disorder characterized by failure to thrive, short stature, developmental delay or intellectual disability, joint laxity, soft skin, and distinctive facial features. "Our second mutation detection strategy involved Sanger sequencing of LZTR1 in seven unrelated patients with a diagnosis of NS and one with the clinically overlapping Costello syndrome." (PMID 30859559, 2019).
COVID-19 (1 paper, 2025). A disease caused by infection with severe acute respiratory syndrome coronavirus 2. "This phenotypic dichotomy, coupled with reports of lethal vascular complications (sudden cardiac death in a LZTR1-variant carrier with COVID-19 comorbidity), strongly implicates RAS/MAPK hyperactivation in endothelial dysregulation and aberrant vasculogenesis." (PMID 40646478, 2025).
Cryptozoospermia (1 paper, 2024). A type of oligozoospermia in which spermatozoa can be detected in an ejaculate only after centrifugation and inspection of the pellet. "However, no ultimate conclusions could be drawn for the phenotypic effect of heterozygous loss-of-function (LoF) variants in LZTR1, detected in one cryptozoospermia subject and one normozoospermia subject in the GEMINI cohort." (PMID 38654924, 2024).
Cushing syndrome (1 paper, 2024). Cushing's syndrome (CS) encompasses a group of hormonal disorders caused by prolonged and high exposure levels to glucocorticoids that can be of either endogenous (adrenal cortex production) or exogenous (iatrogenic) origin. "Lastly, an LZTR1 splice site mutation (c.791 + 1G > A), as well as gain of chromosomes 5 and 7, was seen in a Cushing syndrome-associated corticotroph tumor with borderline grade 2–3 features (Specimen 12A)." (PMID 39388031, 2024).
hereditary cancer (1 paper, 2025). Malignant neoplasms occurring in families at a rate greater than that expected by chance and caused by germline mutations in a specific gene. "LP/P findings in pleiotropic genes linked to human development and hereditary cancer (TSC1, PHOX2B, WT1, SPRED1, NF1, LZTR1, HOXB13) were identified in several patients with syndromic phenotypes." (PMID 40060932, 2025).
Hyperkeratosis (1 paper, 2025). Hyperkeratosis is a histopathological term defining a thickened stratum corneum and may be present in many different skin conditions, with many possible overlaps. "Histological examination of the skin lesions in Lztr1-deficient mice showed diminished hyperkeratosis and parakeratosis, decreased epidermis thickness, and a decrease in the number of proliferative KCs in the basal layer." (PMID 41162356, 2025). "We demonstrated that depletion of CD8+ T cells ameliorates the disease severity in control mice, while abolishing CD8+ T in Lztr1-deficient mice had no additive impact on disease severity (as measured by PASI), epidermal thickness, inflammatory response, or hyperkeratosis." (PMID 41162356, 2025).
metastatic melanoma (1 paper, 2022). A melanoma that has spread from its primary site to another anatomic site. "Finally, we investigated whether overexpression of LZTR1 or CRKL releases normal human melanocytes from their dependency on growth factors, a common phenotype of metastatic melanoma cells." (PMID 35197475, 2022).
myeloid leukemia (1 paper, 2024). A clonal proliferation of myeloid cells and their precursors in the bone marrow, peripheral blood, and spleen. "LZTR1 encodes an adaptor for a ubiquitin-ligase that degrades the RAS-GTP protein RIT1, and interestingly, mutations within the LZTR1 minor intron or activating mutations in RIT1 have been described in the Rasopathy Noonan syndrome as well as myeloid leukemias." (PMID 39316554, 2024).
nerve sheath tumors (1 paper, 2025). "The clinical phenotypes related to LZTR1 variants are mostly demonstrated as nerve sheath tumors." (PMID 40724954, 2025).
pancreatic adenocarcinoma (1 paper, 2026). "Conversely, most adenocarcinomas, such as colon (COAD, blue) and pancreatic adenocarcinomas (PAAD, black) had a low prevalence of KRAS A146 mutations and were not responsive to LZTR1 knockout in DepMap." (PMID 41542462, 2026).
Parkinson disease (1 paper, 2024). A progressive degenerative disorder of the central nervous system characterized by loss of dopamine producing neurons in the substantia nigra and the presence of Lewy bodies in the substantia nigra and locus coeruleus. "We consider two possible explanations for this co-occurrence: our patients might present with LZTR1-related conditions and independently have Parkinson’s disease; alternatively, LZTR1 pathogenic variants could confer susceptibility to Parkinson’s disease." (PMID 39062695, 2024). "The initial report of Parkinson’s disease in our case could stem from the fact that LZTR1-related disorders are primarily reported in pediatric patients, and Parkinson’s disease is potentially a late-onset feature." (PMID 39062695, 2024).
psoriasis (1 paper, 2025). An autoimmune condition characterized by red, well-delineated plaques with silvery scales that are usually on the extensor surfaces and scalp. "Remarkably, our data demonstrated a specific impairment in the differentiation of Tc17 cells within the epidermis of Lztr1-deficient mice, accompanied by decreased expression of T activation-related proteins in psoriasis, such as CTLA-4, PD-1, IL22 and TNF-α 12,38,39." (PMID 41162356, 2025). "Taken together, through both the short-term psoriasis model and the rechallenge model, our data identify LZTR1 as a novel driver of pro-inflammatory KC subsets that amplifies autoantigen presentation and promotes the activation of both CD8+ TRM and Tc17 cells." (PMID 41162356, 2025). "To assess the role of LZTR1 in psoriasis pathogenesis, we applied topical IMQ treatment for 6 consecutive days to the back skin of mice." (PMID 41162356, 2025). "To determine the relationship between LZTR1 and inflammatory KC subset in psoriasis, we performed immunofluorescence (IF) staining on skin sections from 10 healthy donors and 20 patients with psoriasis." (PMID 41162356, 2025). "Moreover, other psoriasis-related pathogenic cytokines like IL22 and TNF-α were downregulated in αβT from Lztr1-deficient mice." (PMID 41162356, 2025). "This relationship between LZTR1 and skin inflammation was further validated in the imiquimod (IMQ)-induced psoriasis-like mouse model." (PMID 41162356, 2025). "In addition, a positive correlation between disease severity in psoriasis (as measured by the Psoriasis Area and Severity Index (PASI)) and LZTR1 protein expression was observed." (PMID 41162356, 2025).
rickets (1 paper, 2024). Bone softening and weakening usually caused by deficiency or impaired metabolism of vitamin D. Deficiency of calcium, magnesium, or phosphorus may also cause rickets. "These molecular defects cause abnormal functions of the cartilage extracellular matrix (COMP), paracrine signalling factors (PHEX, FGFR3-related rickets), transcriptional regulation (LZTR1), histone methylation (KMT2A), posttranslational modification (NAA15), and mtDNA replication and repair (POLG)." (PMID 39415983, 2024).
uterine corpus endometrial carcinoma (1 paper, 2023). A endometrial carcinoma (disease) that involves the body of uterus. "For example, retention of intron 15 of LZTR1, a TSG that negatively regulates RAS signaling through ubiquitination, was upregulated in COAD, STAD, and uterine corpus endometrial carcinoma (UCEC) tumor samples." (PMID 38067392, 2023).
ZTTK syndrome (1 paper, 2025). "In 2/61 cases, RNA-seq revised diagnoses (EPG5 to LZTR1 in an individual with a Noonan syndrome-like disorder) and discovered an additional relevant gene (CEP120 in addition to SON in an individual with ZTTK syndrome)." (PMID 40593860, 2025).
infection (83 papers, 2008 to 2025). The state of being infected such as from the introduction of a foreign agent such as serum, vaccine, antigenic substance or organism. "Nevertheless, within 2–3 days after infection, we noticed a striking induction of anchorage-independent growth, observed as cells overexpressing LZTR1 or CRKL formed three-dimensional clusters in 2D and 3D collagen cultures (top and bottom rows, respectively)." (PMID 35197475, 2022).
tumor (44 papers, 2017 to 2026). "Collectively, these findings define an EMP-related molecular and phenotypic state associated with LZTR1 deficiency in Hep3B cells, providing insight into how LZTR1 loss reshapes tumor cell behavior in HCC." (PMID 41752002, 2026). "We also found a significant correlation (R2=0.6612; p<0.0001) between the frequency of A146 mutations in tumor types and the magnitude of LZTR1’s tumor suppressor effect." (PMID 41542462, 2026). "We observe significant LOH in this patient’s tumor, implicating a novel role for LZTR1 splice variants in AT/RT tumorigenesis." (PMID 39974082, 2025). "The relevance of the germline LZTR1 variants in patient 2 must be interpreted by taking into account the allelic status of somatic variants in tumor tissues." (PMID 39857711, 2025). "A detailed family history, clinical examination and genetic diagnostics revealed a mutation in the LZTR1 gene, which led to the re-diagnosis of all the patient's tumours, which turned out to be exclusively HNS at different locations." (PMID 41247561, 2025). "As a molecular mechanism of tumor metastasis promotion due to LZTR1 deletion, we showed that LZTR1 deficiency promotes EMT induction and ECM deposition in vitro and in vivo." (PMID 37626065, 2023). "To investigate the influence of LZTR1 deficiency on tumor metastasis, we injected A549-WT or A549-KO cells into the tail vein of BALB/c nude mice and examined their lung metastasis potential." (PMID 37626065, 2023). "The observed increase in tumor metastasis and collagen deposition due to LZTR1 deficiency is valuable for understanding the influence of LZTR1 mutations on cancers." (PMID 37626065, 2023). "In summary, the loss of LZTR1 promoted tumor growth and metastasis through the activation of the RAS/MAPK signaling pathway, EMT induction, and ECM deposition." (PMID 37626065, 2023). "While CRKL has been linked to tumor growth as a candidate oncogene in several human malignancies, including lung adenocarcinoma, LZTR1 is generally considered a tumor suppressor." (PMID 35197475, 2022). "Using a computational platform, LZTR1 was identified as a tumor suppressor gene, with somatic mutations in this gene driving glioblastoma." (PMID 35840934, 2022). "LZTR1 (OMIM 600574), encoding leucine zipper-like transcription regulator 1 (LZTR1), was proposed as a tumor suppressor gene belonging to the BTB-Kelch superfamily." (PMID 35840934, 2022). "Here, we report the presence of the SH3PXD2A-HTRA1 gene fusion for the first time in SWNTS-SWNs and show that its prevalence is significantly associated with germline LZTR1 mutations and tumor-associated pain." (PMID 33025139, 2021). "Somatic loss of the wild-type LZTR1 allele is predicted to lead to biallelic loss of LZTR1 in tumours of germline mutation carriers." (PMID 27921248, 2017). "However, in addition to the EWSR1::VGLL1fusion, our patient’s tumor had a nonsense mutation in LZTR1, oneof the two genes with germ-line mutations implicated in non-NF2 associatedschwannomatosis." (PMID 41522855, 2026). "Furthermore, acting like a tumor-suppressor gene, NS individuals with LZTR1 variants need a more careful follow-up because of the potential higher risk of malignant tumors." (PMID 38689733, 2024). "Here, we show that LZTR1 deficiency increases tumor growth and metastasis." (PMID 37626065, 2023). "Given that NS is associated with a higher incidence of cancer and the LZTR1 gene acts as a tumor suppressor, it makes sense that somatic or germline loss of function variants in the LZTR1 gene may be associated with increased incidence of CGCG." (PMID 36291422, 2022). "However, the type of the LZTR1 mutation would appear to influence LZTR1 protein expression in tumours." (PMID 27921248, 2017).